TLR5 (toll like receptor 5)
Diseases named in the same sentence as TLR5 in open-access papers (continued):
Sharing a sentence is not in itself a finding about the gene and the disease.
breast carcinoma (continued). "The canonical ligand for TLR5, flagellin, was shown to slow breast cancer cell proliferation rates as well as rates of tumor growth in mouse xenograft models." (PMID 35805158, 2022). "Mechanistically, an earlier report pioneered the idea that microbiota can dictate the prognosis of extraintestinal ovarian and breast cancers via an effect on Toll-like receptor 5 (TLR5)." (PMID 33963313, 2021). "The TLR5 agonist, flagellin, suppresses breast cancer by induction of caspase-1 activation-dependent pyroptosis." (PMID 33747948, 2021). "For example, even though TLR5 is overexpressed in both gastric and breast cancers, it has opposite effects as it suppresses the proliferation of breast cancer and induces the growth of gastric cancer cells." (PMID 33747948, 2021). "TLR5 signaling in breast cancer downregulates cyclins B1, D1, and E2 thus inhibiting the proliferation of the tumor cells." (PMID 32012718, 2020). "The treatment of breast cancer cells with TLR5 agonist (flagellin) activated the intrinsic signaling pathway which led to the inhibition of anchorage-independent growth and cell-proliferation." (PMID 32012718, 2020). "Remarkably, we found SNP rs5744168 and the expression of TLR5 in human breast carcinomas are related to breast cancer occurrence and its clinical features." (PMID 29179462, 2017). "Among the 256 breast cancer tissue samples tested in a microarray, 161 (62.9%) were positive for TLR5, and TLR5 was highly expressed in 66 (25.8%) tumor samples." (PMID 29179462, 2017). "In the present study, our examination of 256 breast carcinomas specimens revealed that TLR5 is overexpressed in breast carcinomas, and that TLR5 overexpression correlated with lymph node metastasis and cancer grade (p<0.01)." (PMID 29179462, 2017). "We consider the combined examination of the epidemiology and TLR5 expression in breast cancer tissues using tissue microarrays an important strength of our study." (PMID 29179462, 2017). "Activation of TLR5 triggered by flagellin in breast cancer lines and in mouse xenograft models stimulates production of proinflammatory cytokines and inhibits cell proliferation and anchorage-independent growth." (PMID 29179462, 2017). "We focused on TLR5 signaling in MCF7 breast adenocarcinoma cells, since TLR5 is highly expressed and is generally responsive in breast cancer cells." (PMID 26220208, 2015). "Taken together, these observations indicate that MAP1S is an autophagic regulator involved in TLR5 signaling in breast cancer cells." (PMID 24466264, 2014). "Our previous results also showed that activation of TLR5 by flagellin elicited strong antitumor activity in breast cancer cells." (PMID 24466264, 2014). "For example, the majority of human breast cancer samples also express TLR5 and there is an elevated expression of TLR5 in certain subtypes of breast carcinomas." (PMID 24932259, 2014). "In this study, we showed that MAP1S acted as a critical regulator in the antitumor activity of TLR5 signaling in breast cancer cells." (PMID 24466264, 2014). "Recently, TLR5 has been found to be highly expressed in breast carcinomas and activation of TLR5-signaling pathway was found to be overly responsive in breast cancer cells by inhibiting cell proliferation and an anchorage-independent growth." (PMID 22295250, 2012). "For instance, Salmonella typhimurium flagellin has been shown to activate the TLR5 signaling pathway, triggering a pro-inflammatory cascade that suppresses breast cancer cell proliferation while promoting immune cell recruitment and activation, thereby augmenting immunotherapeutic efficacy." (PMID 40497049, 2025). "Activation of TLR5 by flagellin has been shown to suppress cell proliferation and tumor growth in breast cancer cells, indicating that TLR5 may serve as a novel therapeutic target for human breast cancer therapy." (PMID 38903515, 2024).
breast carcinoma (continued). "Further research is needed to fully elucidate the mechanisms by which TLR5 signaling can inhibit breast cancer progression and to explore the potential therapeutic applications of TLR5 agonists or antagonists in combination with other immunotherapeutic approaches." (PMID 38903515, 2024). "Research suggests that TLR5 expression may vary among different subtypes of breast cancer and could have diverse effects on tumor progression and the immune response to cancer." (PMID 38903515, 2024). "Similarly, in breast cancer, TLR5 activation in vitro inhibited tumor cell proliferation and colony formation by decreasing cyclin B1, cyclin D1 and cyclin E2 expression and increasing CDK inhibitor p27." (PMID 37112730, 2023). "TLR5 is highly expressed in breast cancer and its signaling plays a crucial role in the cancer." (PMID 36539522, 2022). "TLR5 was substantially expressed in mouse xenograft breast carcinomas." (PMID 35328602, 2022). "To understand whether the downregulation of TLR5 could promote breast cancer metastasis and invasion, we detected EMT markers and its signal pathway, TRAF6 and SOX2." (PMID 31852883, 2019). "So, further in vitro and in vivo investigations about TLR5 in breast cancer are required." (PMID 31576678, 2019). "Our data in vitro showed that TLR5 expressed in breast cancer could serve as a reporter of cancer invasiveness." (PMID 31852883, 2019). "The immunohistochemistry results indicated that TLR5 is often overexpressed in breast cancer." (PMID 29179462, 2017). "Within breast cancer cells, TLR5 was mainly localized in cytoplasm." (PMID 29179462, 2017). "Over 60% of breast carcinomas expressed TLR5 protein in this study." (PMID 29179462, 2017). "We then wanted to determine whether autophagy can regulate the TLR5 signaling pathway in breast cancer cells." (PMID 24466264, 2014). "Also, flagellin–TLR5 signaling in human breast cancer cells reduces cell proliferation and anchorage-independent growth in human breast cancer xenografts." (PMID 24723911, 2014). "Targeting TLR5 signaling in breast cancer represents a novel strategy in cancer immunotherapy." (PMID 24466264, 2014). "In this study, we focus on the role of MAP1S in TLR5-induced suppression of breast cancer." (PMID 24466264, 2014). "However, TLR5 is most likely to play an anti-tumor role in breast cancer development." (PMID 38903515, 2024). "Additionally, the specific breast cancer subtype and the stage of the disease may also influence the outcome of TLR5 activation." (PMID 38903515, 2024). "Additionally, TLR5 agonist flagellin has been found to inhibit the cell state of activation and induce autophagy, and the autophagy protein MAP1S (Microtubule Associated Protein 1S) has been shown to regulate the flagellin/TLR5 signaling pathway in breast cancer cells." (PMID 38903515, 2024). "However, the roles of TLR5 in breast cancer may be attributed to the complex interplay between the tumor cells, the tumor microenvironment, and the host immune system." (PMID 38903515, 2024). "However, the WT protein led to the autophagy of breast cancer cells by elevating gene expression and activating the TLR5 pathway, which may be a good candidate as an anticancer peptide." (PMID 36539522, 2022). "Hence, additional analyses of TLR5 on breast cancer in vitro and in vivo are required." (PMID 31852883, 2019). "Notably, expression of TLR5 is enhanced in many types of carcinomas, including breast cancer." (PMID 29179462, 2017). "Besides, TLR5 was identified as highly expressed and activated in breast carcinomas." (PMID 24932259, 2014). "A subsequent study in breast cancer cells showed that flagellin induced autophagy by activating MAP1 S, which regulates the TLR5 signaling through enhancement of NF-κB activity and cytokine secretion." (PMID 37112730, 2023).
breast carcinoma (continued). "We observed that MAP1S levels were up-regulated in response to flagellin treatment in human breast carcinomas and MAP1S regulated cytokine expression induced by TLR5 signaling." (PMID 24466264, 2014). "Herein we explored combinations of TLR5 agonists and immune checkpoint therapy (ICT) using the immunogenic 4T1 breast cancer solid tumor model and the poorly immunogenic B16-F10 melanoma tumor model, both highly aggressive cancers and refractory to standard therapies." (PMID 36635337, 2023). "The TLR5 agonist entolimod was reported to induce CD8+ T cell responses through NK-dendritic cell axis within the liver, which resulted in a potent inhibition of liver metastasis of colon and mammary cancers." (PMID 33171765, 2020). "Specifically, CD44 and ALDH1, two important breast CSC markers, increased 2- to 17-fold in all cell lines examined, suggesting that TLR3 activation, but not TLR5, 7, and 8, associates with CSC properties in different subtypes of breast cancer cells." (PMID 25257174, 2015). "Furthermore, activation of TLR5 by flagellin in breast cancer cells has been shown to alter the production of proinflammatory cytokines, and this creates potent antitumor activity in breast cancer, which may serve as a novel therapeutic target for human breast cancer therapy." (PMID 24932259, 2014). "In the early stage of TLR5 activation, MAP1S modulated the production of proinflammatory cytokines and unknown soluble factors to elicit potent antitumor activity in breast carcinomas." (PMID 24466264, 2014). "In agreement with this study, we observed that elevated MAP1S levels were accompanied by degradation of MyD88 and attenuation of MyD88-dependent transcription factor activation, suggesting that MAP1S provides negative feedback regulation in the TLR5 signaling pathway of breast cancer cells." (PMID 24466264, 2014). "In this study, we found TLR5 agonist flagellin inhibited the cell state of activation and induced autophagy, and reported that autophagy protein MAP1S regulated the flagellin/TLR5 signaling pathway in breast cancer cells through enhancement of NF-κB activity and cytokine secretion." (PMID 24466264, 2014). "In contrast, TLR5 and IGF2R are consistently upregulated in heart failure patients not who have breast cancer." (PMID 37684436, 2023). "Initially, our results confirmed the expression of TLR5 in a human monocyte line (THP-1) and isolated human CD14+ monocytes (Mo) using flow cytometry; in addition, the MDA-MB-231 breast cancer line was used as non-immune cell control." (PMID 36903639, 2023).
Sepsis (28 papers, 2013 to 2026). Sepsis is defined as life-threatening organ dysfunction caused by a dysregulated host response to infection. "TLR5 agonists are known to bind TLR5 and attenuate key pathological processes in bleeding and sepsis caused by hematopoietic and gastrointestinal system injury." (PMID 39006841, 2024). "Six core genes, ELANE, IL1R2, RAB13, RNASE3, FCGR1A, and TLR5, have been linked to sepsis prognosis." (PMID 39655195, 2024). "However, high expression of FCGR1A and TLR5 was associated with increased survival rates in the sepsis group compared to those in the control group." (PMID 39655195, 2024). "Allelic variants of TLR5 may predispose infants to sepsis, and high-level expression of TLR5 in septic individuals is positively linked with more severe disease (82, –, 84)." (PMID 27303721, 2016). "The authors concluded that the allelic variants PLA2G2A, TLR2, TLR5 and IL-10 could influence the risk of sepsis among preterm infants." (PMID 24310803, 2013). "Toll-like receptor 5 (TLR5) can exacerbate sepsis and is decreased in monocytes of sepsis survivors." (PMID 41158471, 2025). "Expanding upon these findings, this study additionally revealed an up-regulation of the TLR-5, -6, and -9 receptors during the progression of sepsis." (PMID 40076895, 2025). "ELANE, IL1R2, RAB13, and RNASE3 promote cell death, whereas FCGR1A and TLR5 facilitate cell survival in sepsis." (PMID 39655195, 2024). "In the sepsis group, FCGR1A and TLR5 were positively associated with survival compared to ELANE, IL1R2, RAB13, and RNASE3, which were adversely associated with survival." (PMID 39655195, 2024). "Through the activation of TLR5, flagellin reduces the production of IL‐1RN, so reducing the severity of sepsis, increasing bacterial clearance, decreasing organ inflammation and injury, and reducing immune cell apoptosis following experimental sepsis." (PMID 38685971, 2024). "The lncRNA MALAT1 can alleviate sepsis in burn-injured patients by regulating miR-214/TLR5; the lncRNA CRNDE is involved in aggravating the inflammatory process of sepsis through the miR-181a-5p/TLR4 axis." (PMID 36274974, 2022). "These novel findings not only established the potential value of application of flagellin as an immunoadjuvant in treating sepsis, but also provided new insights into targeted therapeutic strategy on the basis of monocyte TLR5 expression in septic patients." (PMID 30944018, 2019). "Therapeutic administration of flagellin increased bacterial clearance, decreased organ inflammation and injury, and reduced immune cell apoptosis after experimental sepsis, in a Toll-like receptor 5 (TLR5)–dependent manner." (PMID 30944018, 2019). "In this study, we investigated the role of flagellin-induced TLR5 activation in controlling the infection during sepsis using the cecal ligation and puncture (CLP) model of abdominal sepsis in mice." (PMID 30944018, 2019). "In both our zebrafish model and human patients with sepsis-like syndromes, the flagellin receptor TLR5 is among the most highly induced pattern recognition receptors." (PMID 27303721, 2016). "SNPs in the genes for TLR2 (rs3804099), TLR5 (rs5744105), IL-10 (rs1800896), and PLA2G2A (rs1891320) were associated with sepsis." (PMID 24310803, 2013). "In summary, these findings suggest that ELANE, IL1R2, RAB13, RNASE3, FCGR1A, and TLR5 may influence the prognosis of patients with sepsis and provide novel insights and potential avenues for the treatment of sepsis." (PMID 39655195, 2024). "Importantly, our findings indicate that high expression levels of ELANE, IL1R2, RAB13, and RNASE3 promote death rates in sepsis, whereas high expression levels of FCGR1A and TLR5 improve the survival rate of patients with sepsis." (PMID 39655195, 2024). "The current study demonstrated that therapeutic treatment with flagellin could prevent the progression of severe sepsis via TLR5." (PMID 30944018, 2019).
Sepsis (continued). "We also clearly demonstrated that the therapeutic effects of flagellin required TLR5, and TLR5 deletion could abolish the beneficial effects of flagellin on sepsis." (PMID 30944018, 2019). "Furthermore, TLR5 is also expressed on other innate cells and organ epithelium and endothelium cells; the regulatory effects of flagellin on these cells in sepsis should be studied in the future work, which is beyond our present study." (PMID 30944018, 2019). "Our study not only established the potential value of the application of flagellin as an immunoadjuvant in treating sepsis, but also provided new insights into targeted therapeutic strategy on the basis of TLR5 expression on circulating monocytes in septic patients." (PMID 30944018, 2019). "Moreover, the post-sepsis group showed alterations in monocyte surface expression of distinct pattern recognition receptors; most pronouncedly seen in a decrease of TLR5 expression." (PMID 27056672, 2016). "However, only a small part of MVPs have relatively large Δβ (|Δβ|> 0.2), and focusing on those with large Δβ, we found that 6 of 26 differentially methylated genes (23.1%) were previously associated with sepsis in the literature, including ALK, ZEB2, MNDA, AIM2, TLR5, and JUNB." (PMID 35242787, 2022). "Furthermore, the hub genes TLR5, FCGR1A, ELANE, GNLY, IL2RB and TGFBR3, which may be associated with the prognosis of sepsis, and their negatively correlated microRNAs, were analysed." (PMID 35332254, 2022). "A total of 1389 DEGs such as NOV, SEPT9, XIST, ESYT1 were upregulated in sepsis, whereas 1657 DEGs such as S100A9, IRAK3, MCEMP1, TLR5, CD177 were downregulated." (PMID 41542228, 2026). "The expression of PD-1; PD-L1; TLR-5, -6, and -9; MYD88; IRAK1; TIRAP; and NFkB was quantified by RT-PCR at 24, 48, and 72 h after CLP-induced sepsis." (PMID 40076895, 2025). "In the two groups of different expression trend modules, the core genes such as CD160, GATA2, GNLY, IL2RB and TGFBR3 were downregulated in the sepsis group, while genes such as ELANE, IL1R1, TLR5, FCGR1A, MAPK14 and PCSK9 were upregulated." (PMID 35332254, 2022). "We also observed that ISM1+ cells express TLR4, TLR5, and TLR9, and, in a mouse model of sepsis induced by P. aeruginosa, we observed that all the LSK and ISM1+LSK cells were affected." (PMID 35402623, 2022). "This was consistent with the MDSC expression of TLR5 and in agreement with the requirement of MyD88 for MDSC expansion during polymicrobial sepsis." (PMID 34208904, 2021). "Some selected genes were significantly higher expressed in sepsis as compared with MBC samples (CD24, CD177, MMP8, and TLR5), and in MBC compared with sepsis (HLA-DRA, CSF1R, and AGAP6/9)." (PMID 32958605, 2020). "Genes that were expressed at high levels in MBC and sepsis patients compared with HC N cells were relevant to immunosuppression and metastasis (ARG1, MMP8, TLR5, and CD177) (green)." (PMID 32958605, 2020). "However, whether TLR5 plays a role in controlling infection during sepsis has yet to be addressed." (PMID 30944018, 2019). "S1PR5, GNLY, CD247, KLRG1, IL-1R2, AUTS2, IL-2Rβ, ARG1, TGFBR3, TLR5 and PRF1 in the top 80 genes in the two modules were located toward the center of the co-expression network, and CD247, IL-2Rβ, TGF-βR3 and IL-1R2 were identified as core genes in sepsis." (PMID 36855106, 2023). "Consequently, the genes TLR5, FCGR1A, ELANE, GNLY, IL2RB and TGFBR3 genes were ultimately identified as hub genes in sepsis." (PMID 35332254, 2022). "The sepsis survivors also demonstrated alterations in monocyte surface expression in pattern recognition receptors (PRR), most pronouncedly observed in decreased Toll-like receptor-5 (TLR-5)." (PMID 34945111, 2021). "The expression of pattern recognition receptors (PRR) on leukocyte surface was not different between the two groups except for TLR-5, which was expressed at a lower level in the sepsis group." (PMID 28770544, 2017).
Sepsis (continued). "Herein, we will review the most popular agonist (TLR3, TLR5, TLR7, TLR8, TLR9) and antagonist (TLR2, TLR3, TLR4, TLR9) agents used in pre-clinical and clinical models of acute and chronic infections, including sepsis." (PMID 24302927, 2013). "Finally, we found that the expression of TLR5 was significantly elevated on the surface of circulating monocytes, but not neutrophils, from patients with sepsis." (PMID 30944018, 2019). "Additionally, there was an increased expression of TLR5 and RAB13 in sepsis, although this change was not statistically significant and was not easily noticeable." (PMID 39655195, 2024). "In sum, all that can be said in general about innate activation in sepsis is that TLR2, TLR4, TLR5, TLR7 and NLRP3 can be, but are not necessarily, activated, while TLR9 may or may not be downregulated." (PMID 33672738, 2021).